NEDD9 (neural precursor cell expressed, developmentally down-regulated 9)
Diseases named in the same sentence as NEDD9 in open-access papers (continued):
Sharing a sentence is not in itself a finding about the gene and the disease.
lung adenocarcinoma (8 papers, 2010 to 2025). A carcinoma that arises from the lung and is characterized by the presence of malignant glandular epithelial cells. "We examined the NEDD9 expression levels from the tissues of human lung adenocarcinomas (LUADs) and squamous-cell carcinomas (LUSCs), Grades 1–3." (PMID 40362444, 2025). "The results from a fluorescent quantitative reverse transcription polymerase chain reaction (fq-PCR) indicated a 10- to 100-fold increase in NEDD9 mRNA expression in highly invasive lung adenocarcinoma cell lines compared to the less invasive cell lines." (PMID 40362444, 2025). "The results from our recent study showed that MEG3 decreased developmentally downregulated protein 9 (NEDD9) and the knockdown of NEDD9 inhibited migration and invasion in human lung adenocarcinoma A549 cells." (PMID 36851033, 2023). "Alternatively, miR-125a-5p overexpression inhibits lung adenocarcinoma cell proliferation and induces cell apoptosis by targeting neural precursor cell expressed, developmentally down-regulated 9 (NEDD9)." (PMID 30813457, 2019). "The aim of the present study was to investigate the invasion- and metastasis-related gene, neural precursor cell expressed, developmentally downregulated 9 (NEDD9), in lung adenocarcinoma tissues and cell lines." (PMID 23226728, 2012). "The western blotting and immunohistochemical evaluations of NEDD9 expression were comparable; the lung adenocarcinoma cases with a high level of NEDD9 protein content also demonstrated intense immunostaining." (PMID 23226728, 2012). "Our results provide evidence that NEDD9 is upregulated in metastatic lung adenocarcinoma and in highly invasive lung adenocarcinoma cell lines, suggesting its potential involvement in regulating cell migration and invasion." (PMID 23226728, 2012). "The levels of NEDD9 in the highly invasive lung adenocarcinoma cell lines (A549 and 95D) were high, whereas the level of NEDD9 in the poorly invasive cell line (SPC-A-1) was low." (PMID 23226728, 2012). "Western blotting was used to evaluate NEDD9 protein expression in three lung adenocarcinoma cell lines." (PMID 23226728, 2012). "In conclusion, we proved that NEDD9 was markedly upregulated in human metastatic lung adenocarcinoma tissues and highly invasive lung adenocarcinoma cell lines." (PMID 23226728, 2012). "NEDD9 expression was significantly increased in highly invasive lung adenocarcinoma cell lines A549 and 95D." (PMID 23226728, 2012). "We analyzed 60 tumors by means of immunohistochemistry, three invasive lung adenocarcinoma cell lines were analyzed by FQ-PCR and western blotting, and provided immunohistochemical and molecular evidence of NEDD9 upregulation in lung adencarcinoma." (PMID 23226728, 2012). "According to FQ-PCR, highly invasive lung adenocarcinoma cell lines demonstrated 10- to 100-fold overexpression of NEDD9 mRNA relative to the less invasive cell line." (PMID 23226728, 2012). "NEDD9 was found to be expressed in the cell nuclei and the cytoplasm of the lung adenocarcinoma cells." (PMID 23226728, 2012). "NEDD9 was found to be expressed in the cell nuclei and the cytoplasm of lung adenocarcinoma cells." (PMID 23226728, 2012). "NEDD9 mRNA expression and protein levels were quantified by fluorescence quantitative reverse transcription-polymerase chain reaction (FQ-PCR) and western blotting in the highly invasive lung adenocarcinoma cell lines A549 and 95D as well as in SPC-A-1 cells with low invasive potential." (PMID 23226728, 2012). "The findings suggest that NEDD9 may be closely related to metastasis of lung adenocarcinoma." (PMID 23226728, 2012). "The expression of NEDD9 was analyzed by the SP method of immunohistochemistry for 60 formalin-fixed and paraffin-embedded (FFPE) lung adenocarcinoma tissues in which 32 cases were metastastic and 28 were without metastases." (PMID 23226728, 2012).
lung adenocarcinoma (continued). "Our results show that NEDD9 is upregulated in the lung tissues from human lung adenocarcinomas (LUADs) and squamous-cell carcinomas (LUSCs) compared to normal lungs." (PMID 40362444, 2025). "Considering the NEDD9 protein expression values, immunohistochemical scoring revealed a statistically significant correlation between metastatic and nonmetastatic lung adenocarcinoma (7±2.86 versus 5±2.67, p<0.001)." (PMID 23226728, 2012). "This study describes NEDD9 expression in lung adenocarcinoma with and without metastasis for the first time." (PMID 23226728, 2012).
glioma (7 papers, 2011 to 2024). A benign or malignant brain and spinal cord tumor that arises from glial cells (astrocytes, oligodendrocytes, ependymal cells). "For instance, REST loss in T98G cells led to a reduction in NEDD9 expression, a marker of glioma invasion potential, and an increase in BEX1 expression, a tumor suppressor gene in malignant glioma." (PMID 38609948, 2024). "Various studies have shown that NEDD9 is highly expressed in malignant tumour tissues, such as glioma, colorectal and liver cancer tissues, and it has been suggested that it plays an important role in tumour invasion, metastasis and migration." (PMID 35549691, 2022). "It has similar expression pattern and prognostic effect to NEDD9, and is related to the prognosis of many cancer patients such as gastric cancer and glioma." (PMID 33195408, 2020). "Out of the 13 signature genes, ATP6V1E1, EIF3D, ERCC1, GPNMB, MTDH, PCNA and NEDD9 have been reported to play crucial roles in various pathways and mechanism of glioma." (PMID 31632497, 2019). "The high levels of NEDD9 expression in GB and in LGG with lower PFS, along with the absence of NEDD9 in normal brain tissue, support the concept that NEDD9 expression is an important requisite for glioma invasion and progression." (PMID 22869051, 2012). "We also identified a novel target of miR-145, NEDD9 and found that its regulation modulates the invasion potential of gliomas." (PMID 22869051, 2012). "We studied the contribution of NEDD9 to glioma progression and invasiveness using real-time PCR to analyze mRNA expression levels in 18 GB specimens, 18 GB-NS cell lines and 27 LGG specimens previously investigated for expression of miR-145." (PMID 22869051, 2012). "NEDD9 is also expressed in a subgroup of low-grade glioma specimens and was show to be correlated with lower patient survival, indicating a relevant role of NEDD9 in glioma progression." (PMID 22869051, 2012).
non-small cell lung carcinoma (7 papers, 2014 to 2025). A group of at least three distinct histological types of lung cancer, including non-small cell squamous cell carcinoma, adenocarcinoma, and large cell carcinoma. "This study describes a novel role for the scaffolding protein NEDD9 in regulating DDR signaling and characterizes its effects on sensitivity to DNA damaging therapies in a non-small cell lung cancer (NSCLC) setting." (PMID 35626121, 2022). "In non-small cell lung cancer cells, MALAT1 binds miR145-5p and decreases its expression, leading to increased NEDD9 protein expression, since miR145-5p targets the 3'-untranslated region (UTR) of NEDD9 mRNA." (PMID 32174966, 2020).
cervical carcinoma (6 papers, 2010 to 2025). A carcinoma arising from either the exocervical squamous epithelium or the endocervical glandular epithelium. "To find a clue of the relationship between NEDD9 protein and human cervical carcinoma, we employed immunohistochemical analysis to determine the expression of NEDD9 protein in human cervical carcinoma tissues and analyzed the association of NEDD9 expression with human cervical carcinoma progression." (PMID 24058594, 2013). "The results of transwell assays showed that NEDD9 shRNA cut down invasive and migratory capability of cervical cancer SiHa and HeLa cells." (PMID 24058594, 2013). "Here, we employed RNAi as a tool to investigate the role of NEDD9 in the progression of cervical cancer." (PMID 24058594, 2013). "Our results suggest that NEDD9 is a late molecular event that participates mainly in the progression or metastasis of cervical cancer." (PMID 24058594, 2013). "Immunofluorescence analysis showed that the protein of NEDD9 was overexpressed in cervical cancer cell lines and distributed mainly in cytoplasm." (PMID 24058594, 2013). "Further, we tried to decide if migration and invasion of cervical cancer cells would be attenuated by reduction of NEDD9 expression via lentivirus-carried shRNA." (PMID 24058594, 2013). "The experimental results showed NEDD9 protein was overexpressed in cervical cancer compared with normal cervical epithelium tissues." (PMID 24058594, 2013). "Our results revealed that NEDD9 protein was overexpressed in most cervical carcinoma tissues and cells compared with normal epithelium tissues and non-tumor keratinocytes." (PMID 24058594, 2013). "Overexpressed NEDD9 promotes cell migration and invasion in cervical cancer cells, probably via regulating tyrosine dephosphorylation of FAK and SRC and the expression of EMT-associated protein E-cadherin." (PMID 24058594, 2013). "The results suggest that Vimentin and E-cadherin are involved in the regulatory role of NEDD9 on cell migration and invasion in cervical cancer cells." (PMID 24058594, 2013). "The aim of this study was to determine if NEDD9 was involved in the progression and metastasis of cervical cancer." (PMID 24058594, 2013). "The siRNA showed strong interference effects against NEDD9 mRNA and protein in cervical cancer SiHa and HeLa cells." (PMID 24058594, 2013). "Western blot analysis showed that NEDD9 was highly expressed in the cervical cancer cell lines, similarly to those of qPCR." (PMID 24058594, 2013). "We found that NEDD9 protein was overexpressed in most cervical carcinoma tissues but poorly expressed in normal cervical epithelium tissues." (PMID 24058594, 2013). "Here we detected NEDD9 expression in human cervical cancer tissues and explored the role of NEDD9 in the progression of cervical cancer." (PMID 24058594, 2013). "Our results suggest that NEDD9 overexpression promotes migration and invasion of cervical cancer cells probably via, at least partially, epithelial-mesenchymal transition (EMT) pathway." (PMID 24058594, 2013). "The results further confirmed that E-cadherin was a suppressive regulatory protein in NEDD9 promoting cell migration and invasion in cervical cancer cells." (PMID 24058594, 2013). "NEDD9 has been reported to enhance the invasion and migration of cervical carcinoma cells." (PMID 40362444, 2025). "NEDD9, a focal adhesion scaffolding protein, has been recently proposed to regulate invasion and metastasis in some cancer types, but unknown in cervical cancer." (PMID 24058594, 2013). "Taking into account HPV infection is an early event in the development of cervical cancer, we believe that NEDD9 may be a late molecular event that participates mainly in the progression or metastasis of cervical cancer." (PMID 24058594, 2013).
cervical carcinoma (continued). "Our findings suggest that NEDD9 is overexpressed in cervical cancer tissues and cells, and overexpressed NEDD9 promotes migration and invasion in cervical carcinoma cells, probably via a positive feedback loop of tyrosine phosphorylation between NEDD9 and FAK or SRC." (PMID 24058594, 2013). "To identify NEDD9 function in cervical cancer cells, we knocked down NEDD9 in SiHa and HeLa cells using a specific siRNA (S: 5' GAG ACA CCA UCU ACC AAG U[dT] [dT] 3', AS: 5' ACU UGG UAG AUG GUG UCU C[dT] [dT] 3'), which was selected from three candidates by qPCR." (PMID 24058594, 2013). "In addition, our data showed that silencing NEDD9 decreased Vimentin expression and increased E-cadherin expression in cervical cancer cells, and vice versa." (PMID 24058594, 2013). "Moreover, inhibiting NEDD9 expression by RNAi attenuated migration and invasion of cervical cancer cells." (PMID 24058594, 2013). "Our results showed that NEDD9 protein was overexpressed in cervical cancer tissues with metastasis." (PMID 24058594, 2013). "In summary, scaffolding protein NEDD9 is overexpressed in cervical cancer tissues and cells." (PMID 24058594, 2013). "Thus, we detected and compared the NEDD9 expression by immunohistochemical analysis in 67 cervical cancer and 22 cervical normal tissues, as well as cervical cancer cell lines and non-tumor keratinocyte line." (PMID 24058594, 2013). "Thus, we observed possible links between E6/E7 and NEDD9 in cervical cancer cells." (PMID 24058594, 2013). "Silencing NEDD9 resulted in tyrosine dephosphorylation of FAK and SRC oncoproteins, and decreased cell migration and invasion in the cervical carcinoma SiHa and HeLa cells." (PMID 24058594, 2013). "Further, we found that NEDD9 overexpression was correlated with lymph node metastasis, histological grading, and FIGO stage of cervical carcinoma patients." (PMID 24058594, 2013). "Overexpression of NEDD9 was correlated with histological grading, lymph node metastasis, and FIGO stage of cervical cancer." (PMID 24058594, 2013). "A similar study on NEDD9, a focal adhesion scaffolding protein, proposed to promote migration and invasion of cervical cancer was found to be independent of any interaction with HPV E6/E7." (PMID 26992219, 2016). "We found in the study that NEDD9 and FAK similarly distributed in cytoplasm of HPV16-positive cervical carcinoma SiHa cells (data not shown), suggesting there perhaps are some special links between NEDD9 and FAK." (PMID 24058594, 2013).
gastric cancer (6 papers, 2014 to 2025). A primary or metastatic malignant neoplasm involving the stomach. "Several studies in the Asian population have linked increased expression of NEDD9 with more aggressive clinical course of gastric cancer." (PMID 33485292, 2021). "Our results are in concordance with previous results investigating association of increased expression of NEDD9 in gastric cancer with lymph node positivity." (PMID 33485292, 2021). "Epithelial Cx43 expression, both epithelial and stromal NEDD9 expression, T and N status were all independently associated with survival in gastric cancer patients." (PMID 33485292, 2021). "The aim of this study is to investigate the involvement of NEDD9 in gastric cancer cell migration under hypoxia and explore the underlying potential molecular mechanisms." (PMID 31019460, 2019). "Very recently, Nedd9, a Crk-associated protein involved in focal adhesion, has been found overexpressed in gastric cancer." (PMID 25395181, 2014). "In addition, very recent studies found that the Crk-associated focal adhesion protein Nedd9 is overexpressed in gastric cancer and tightly associated with metastasis." (PMID 25395181, 2014). "Expression of Nedd9 is tightly associated with gastric cancer progression, particularly metastasis." (PMID 25395181, 2014). "In our study, we were also interested in expression of Cx43 on both, epithelial and stromal gastric cancer cells and its possible link to NEDD9." (PMID 33485292, 2021). "Our scope was to detect the expression of Cx43 and NEDD9 in epithelial and stromal gastric cancer compartments and its relation to tumor progression and lymph node metastases." (PMID 33485292, 2021). "In all, these data suggested that by interaction with the MICAL1, NEDD9 maintained MICAL1 stability under hypoxia by reducing its degradation in gastric cancer cells." (PMID 31019460, 2019). "The mRNA and protein level of NEDD9 increased as a result of hypoxia in gastric cancer cell lines BGC-823 and SGC-7901 while decreased levels of NEDD9 caused reduced cell migratory potential in response to hypoxia." (PMID 31019460, 2019). "The results here demonstrated that hypoxia promoted gastric cancer cell migration by positively regulating the expression of NEDD9 and its subsequent binding to MICAL1." (PMID 31019460, 2019). "By analysis of gastric cancer specimens, we noticed a positive correlation between NEDD9 and MICAL1 protein expressions." (PMID 31019460, 2019). "Immunohistochemistry analysis in the gastric cancer tissue microarray showed a positive correlation between NEDD9 and MICAL1 expressions (r = 0.55)." (PMID 31019460, 2019). "Understanding the NEDD9 regulatory pathway in cell migration will provide not only new insights into cancer metastasis but also therapeutic targets for gastric cancer." (PMID 31019460, 2019). "The present study provides evidence that hypoxia promotes NEDD9 protein expression in gastric cancer cells." (PMID 31019460, 2019). "Meanwhile, silencing of NEDD9 suppressed the increased cell migration stimulated by hypoxia, confirming that NEDD9 was involved in the migration of gastric cancer cells under hypoxia." (PMID 31019460, 2019). "The increase in the proportion of the 105 kDa isoform in BGC-823 and 115 kDa isoform in SGC-7901 indicated a relative different increment of NEDD9 phosphorylation status in various types of gastric cancer cells under hypoxia." (PMID 31019460, 2019). "Knockdown of either NEDD9 or MICAL1 in gastric cancer cells inhibited hypoxia-induced ROS production." (PMID 31019460, 2019). "In all, the results above indicated that the increased expression of NEDD9 was essential for hypoxia-stimulated gastric cancer cell migration." (PMID 31019460, 2019). "Under hypoxic conditions, silencing of NEDD9 caused reduction in the stability of MICAL1 protein, while depletion of MICAL1 also inhibited the migration of NEDD9-overexpressing gastric cancer cells." (PMID 31019460, 2019).